PMPCB (peptidase, mitochondrial processing subunit beta)
Description:
Catalytic subunit of the essential mitochondrial processing protease (MPP), which cleaves the mitochondrial sequence off newly imported precursors proteins (Probable). Preferentially, cleaves after an arginine at position P2 (By similarity). Required for PINK1 turnover by coupling PINK1 mitochondrial import and cleavage, which results in subsequent PINK1 proteolysis.
Synonyms: MPPB; MPPP52; MAS1; beta-MPP; MPP11; P-52
Tractability: PROTAC: ubiquitination databases record sites on it; its protein half-life has been measured.
Target class: Enzyme; Hydrolase
Gene: Protein-coding gene on chromosome 7 (103,295,717 to 103,331,818, forward strand). Ensembl gene ENSG00000105819.
Subcellular location: Mitochondrion matrix
Subcellular location (Human Protein Atlas): Mitochondria
Pathways (Reactome):
Protein localization: Mitochondrial protein import
Transport of small molecules: Processing of SMDT1
Gene Ontology:
Molecular function: metalloendopeptidase activity; signal peptidase activity; metal ion binding
Biological process: protein processing; mitochondrial calcium ion transmembrane transport; protein localization to mitochondrion; proteolysis
Cellular component: mitochondrial matrix; mitochondrion; mitochondrial processing peptidase complex
Genetic constraint (gnomAD): Loss-of-function variants: 32 observed, 39.6 expected, observed/expected ratio (o/e) 0.81, 90% interval 0.61 to 1.09. The upper end of that interval is the gene's LOEUF score, 1.09, which puts it in group 4 of 6, group 1 being the genes least tolerant of losing a copy. Missense variants: 420 observed, 440.56 expected, observed/expected ratio (o/e) 0.95, 90% interval 0.88 to 1.03. Synonymous variants: 147 observed, 152.12 expected, observed/expected ratio (o/e) 0.97, 90% interval 0.84 to 1.11.
Homologues: Orthologues: chimpanzee PMPCB (99% identical), macaque PMPCB (98% identical), dog PMPCB (92% identical), guinea pig PMPCB (92% identical), pig PMPCB (90% identical), mouse Pmpcb (90% identical), rat Pmpcb (90% identical), rabbit PMPCB (80% identical), tropical clawed frog pmpcb (80% identical), zebrafish pmpcb (77% identical), Drosophila melanogaster UQCR-C1 (66% identical), Caenorhabditis elegans mppb-1 (45% identical). Paralogues in human: UQCRC1 (55% identical), PMPCA (31% identical), UQCRC2 (24% identical), NRDC (24% identical), PITRM1 (21% identical), IDE (20% identical).
Diseases named in the same sentence as PMPCB in open-access papers:
PMPCB is named in the same sentence as 11 diseases in open-access papers, as found by Europe PMC text mining. Sharing a sentence is not in itself a finding about the gene and the disease. The quoted sentences say what the papers report.
Ataxia (3 papers, 2023 to 2024). Ataxia refers to impaired coordination of voluntary muscle movement. "We report the first splice site variant in the PMPCB gene in a 39-year old individual who experienced developmental regression and ataxia following otitis media in childhood." (PMID 38374165, 2024). "Although PMPCB was previously only associated to a severe recessive mitochondrial disorder with ataxia phenotypes, we propose that loss-of-function of a single allele can lead to a milder late-onset dominant neurodegenerative phenotype." (PMID 38239855, 2023). "While further functional investigation and additional patients will help understand the role of PMPCB in ataxic phenotype, we posit that ataxia gene panels would benefit from the inclusion of the gene in a similar fashion to its partner, PMPCA." (PMID 38239855, 2023).
breast carcinoma (1 paper, 2021). "Under the same experimental conditions, we detected a partial loss of mitochondrial mass in MCF7 cells—an epithelial breast cancer cell line, when measuring the area covered by the mitochondrial matrix marker PMPCB." (PMID 33820826, 2021).
mitochondrial disease (2 papers, 2022). "In humans, mutations in either PMPCA or PMPCB cause mitochondrial diseases that are characterized by neurological disorders with early childhood onset and a severe neurodegenerative course." (PMID 35163221, 2022).
heart disease (1 paper, 2021). "The remaining proteins, i.e., EEF1D, TIMM13, and PMPCB, are involved in transferring aminoacyl-tRNAs, regulating heat-shock response, and maintaining mitochondrial functions, but their roles in heart disease contexts have not been investigated." (PMID 34211507, 2021).
neurological disease (1 paper, 2020). "Variants in PMPCB, which encodes the catalytic subunit of mitochondrial processing protease, induce a progressive neurological disease in early childhood." (PMID 33426505, 2020).
PMPCB also shares sentences with these, for which no sentence is quoted: Cerebellar atrophy (2 papers); cardiomyopathy (1); Leigh syndrome (1); leukemia (1); liver cancer (1); otitis media (1).